RNU6-503P (RNA, U6 small nuclear 503, pseudogene)
Gene: Small nuclear RNA gene on chromosome 1 (75,538,015 to 75,538,119, reverse strand). Ensembl gene ENSG00000252338.
Homologues: Orthologues: chimpanzee U6 (99% identical), pig U6 (70% identical). Paralogues in human: RNU6-474P (70% identical), RNU6-921P (70% identical), RNU6-116P (70% identical), RNU6-522P (70% identical), RNU6-541P (70% identical), RNU6-654P (70% identical), RNU6-663P (70% identical), RNU6-905P (70% identical), RNU6-1011P (69% identical), RNU6-592P (69% identical), RNU6-1029P (68% identical), RNU6-1060P (68% identical), and 1285 more.